CX3CR1 (C-X3-C motif chemokine receptor 1)
Diseases named in the same sentence as CX3CR1 in open-access papers (continued):
Sharing a sentence is not in itself a finding about the gene and the disease.
diabetes (continued). "The aim of this study was to examine comparatively (diabetes class C—complicated versus normal pregnancy) the correlation between CX3CL1 content in placental tissue, the mean CX3CR1 expression, and density of the network of placental microvessels." (PMID 23956503, 2013). "Similarly, hsa-miR-3059-5p, Asthma, Diabetes Mellitus, NFIL3, Simvastatin, and Cadmium have an interaction relationship centred on CX3CR1." (PMID 40461634, 2025). "Specifically, genes and cell surface markers involved in trans-endothelial migration and the recruitment of CD163+ monocytes were significantly suppressed and the expression of chemokine receptors CX3CR1, CXCL7 (PPBP), and CCR5 were down-regulated in those with diabetes complications." (PMID 39337580, 2024). "This supports that the absence of CX3CR1 recruits bone marrow derived immune populations into the retina, as well as reduced IL-10 expression, which is upregulated during clearance of diabetes-induced apoptotic cells." (PMID 36869375, 2023). "Several studies have shown that CX3CR1 and CX3CL1 are upregulated in the kidneys of patients with diabetes, accompanied by an increase in urea, creatinine, A/C ratio, HbA1C, and IgG; however, the concrete mechanism of CX3CL1-CX3CR1 recruiting T cells requires further exploration in DKD." (PMID 36776877, 2023). "In contrast, PLX-5622 treatment in diabetic CX3CR1-KO and hCX3CR1I249/M280 mice did not alleviate TUJ1+ axonal loss caused by diabetes." (PMID 37033925, 2023). "Our previous studies performed on placentas from diabetes-complicated pregnancies did not reveal the presence the CX3CR1 on syncytiotrophoblastic cells, only placental endothelial cells were positive for CX3CR1." (PMID 33496844, 2021). "CX3CR1 and CX3CL1 are upregulated in the kidney in diabetes." (PMID 34009468, 2021). "Fibrinogen deposition in retinal blood vessels of Akita mice was not evident in acute (6 weeks) stages of diabetes regardless of CX3CR1 genotype." (PMID 28119571, 2016). "Conversely, inducing endotoxin-mediated systemic inflammation during acute diabetes resulted in fibrinogen deposition in the retina, a phenotype that was exacerbated in mice lacking CX3CR1 signaling." (PMID 28119571, 2016). "We report that following chronic (16 weeks), but not acute (6 weeks) diabetes, fibrinogen leakage was evident in the retina irrespective of the CX3CR1 genotype." (PMID 28119571, 2016). "Diabetes induced a significant increase in GFAP+ percent immunoreactive area in CX3CR1-WT (47.64 ± 5.179, 2-way ANOVA P<0.0001) and CX3CR1-KO (49.60 ± 4.794, 2-way ANOVA P<0.0001) mice in comparison to ND controls, (CX3CR1-WT 29.969 ± 3.127 and CX3CR1-KO 30.325 ± 2.976)." (PMID 37033925, 2023). "The reduction in neuronal densities correlated with morphological microglial activation, and the present study provides novel insights into the inflammatory reaction in the context of diabetes using the Ins2Akita model and dysregulated microglial responses in absence of CX3CR1 signaling." (PMID 26514658, 2015). "Whether monocytes expressing lower levels of CX3CR1 contribute to insulin resistance and diabetes in the frail elderly is not known." (PMID 25105870, 2014). "Results from this study are consistent with former discoveries in the context of diabetes using the Ins2Akita model, STZ model, and microglia depletion model showing dysregulated microglial responses in absence of CX3CR1/FKN signaling." (PMID 38311721, 2024).
retinal degeneration (30 papers, 2010 to 2025). Degeneration of the retina. "Previous studies have shown that the mice with Cx3cr1 deficiency developed retinal degeneration by 1–2 years of age, and the pathology is known to be related to increased subretinal infiltration of CCR2+ phagocytes and the impairment in their removal." (PMID 33602265, 2021). "Taken together our data demonstrates that Cd36 deficiency inhibits retinal inflammation and retinal degeneration in Cx3cr1 knockout mice." (PMID 31969887, 2019). "Previous studies have shown that CCL2/CX3CR1 deficient mice on C57BL/6N background (with rd8 mutation) have an early onset (6 weeks) of spontaneous retinal degeneration." (PMID 23637822, 2013). "Subretinal accumulation of Cx3cr1 deficient MPs is associated with retinal degeneration and more precisely photoreceptor degeneration." (PMID 24142887, 2013). "Our data demonstrates that the genetic inactivation of either Ccl2 and/or Cx3cr1 chemokine signalling differentially modulates the severity of the retinal degeneration caused by the Crb1RD8/RD8 mutation at 8 weeks of age." (PMID 22545116, 2012). "In Cx3cr1 knockout mice, accumulation of subretinal macrophages/microglia is associated with a marked, progressive age-related retinal degeneration." (PMID 22545116, 2012). "Previous studies using injections of recombinant IL-1ra, an endogenous antagonist for IL-1r1, have suggested a role for IL-1β in propagating retinal degeneration, using models of photo-oxidative damage in Cx3cr1-deficient mice, laser-induced CNV, and retinitis pigmentosa." (PMID 28438165, 2017). "The activation of canonical Wnt signaling might contribute to the focal retinal degeneration of mouse models with Ccl2 and Cx3cr1 deficiency, and intravitreal anti-LRP6 antibody therapy might be beneficial via deactivation of the canonical Wnt pathway." (PMID 26476672, 2015). "Moreover, resident microglia amass in the subretinal space of CX3CR1-deficient mice at sites of drusen formation and retinal degeneration." (PMID 23833031, 2013). "Also for Cx3cr1 deficient mice a pronounced age-related retinal degeneration has been reported." (PMID 23232206, 2013). "The role of fractalkine/CX3CR1 signaling has been suggested to play a crucial role in mediating microglia recruitment to apoptotic photoreceptors in the light induced retinal degeneration model." (PMID 36088481, 2022). "Both control (Arr1+/+Cx3cr1+/D2) and experimental mice (Arr1−/− Cx3cr1+/D2) were then exposed to continuous room light, initiating retinal degeneration in the Arr1−/− mouse." (PMID 34654439, 2021). "For instance, transplantation of mesenchymal stem cells engineered to secrete CX3CR1 in the subretinal space inhibited microglial activation and expression of pro-inflammatory factors in light-induced retinal degeneration in rats." (PMID 31481963, 2019). "In contrast, deletion of CX3CR1 in an rd10 retinal degeneration mouse model augmented microglial activation and infiltration into the photoreceptor layers with concomitant increase in photoreceptor demise." (PMID 31481963, 2019). "Compared to normal mice, retinal degeneration in CX3CR1−/− mice was paralleled by increased CCL2 induction and retinal CCR2+ monocytes infiltration." (PMID 28320442, 2017). "CCR2 deletion blocked retinal degeneration, suggesting that CX3CR1 usually represses CCL2 over-induction and recruitment of neurotoxic levels of CCR2+ monocytes." (PMID 28320442, 2017). "Cx3cr1 deletion also increases intraretinal and subretinal MP accumulation in diabetes and intraretinal MP accumulation and retinal degeneration in a paraquat-induced retinopathy model." (PMID 24142887, 2013). "Ccl2/Cx3cr1 double knockout (CCDKO) mice show an early onset retinal degeneration and have been suggested as a model for AMD." (PMID 22545116, 2012).
retinal degeneration (continued). "Taken together, these findings suggest that fractalkine/CX3CR1 represents a potential novel therapeutic target to regulate inflammation and photoreceptor survival in light-induced retinal degeneration." (PMID 22536384, 2012). "In both CX3CR1-knockout mice and mice with a loss-of-function variant of the human CX3CR1 gene, the depletion of microglia did not reduce retinal degeneration or alter the morphology of microglia, as observed in wild-type CX3CR1 mice." (PMID 39940727, 2025). "This suggests that during normal ageing individual or combined genetic defects in CCL2 or CX3CR1 signalling alone are not sufficient to drive photoreceptor loss and age-related retinal degeneration above basal levels." (PMID 23232206, 2013). "In this study we therefore compare the newly established (rd8 mutation-free) chemokine knockout mouse lines to investigate whether individual or combined defects in Ccl2 and/or Cx3cr1 signalling result in retinal degeneration with age." (PMID 23232206, 2013). "Our data reveals that the combined genetic deficiencies of CCL2 and CX3CR1 as well as the individual deficiencies are not sufficient to induce age-related retinal degeneration up to 14 months." (PMID 23232206, 2013). "This indicates that neither Ccl2 nor Cx3cr1 deficiency alone nor the combined double knockout of both chemokines leads to a pronounced early onset retinal degeneration." (PMID 22545116, 2012). "In order to understand phenotypic discrepancies in different chemokine knockout lines and to study how defects in Ccl2 and/or Cx3cr1 signalling contribute to the described early onset retinal degeneration, we defined primary and secondary pathological events in CCDKO mice." (PMID 22545116, 2012). "We now provide evidence that the early onset retinal degeneration, observed in these CCDKO knockout mouse lines as well as in all re-derived “affected” Ccl2 and Cx3cr1 and Ccl2/Cx3cr1 double knockout mice, is caused by a third independent autosomal recessive locus." (PMID 22545116, 2012). "This evidence led us to hypothesize that the fractalkine–CX3CR1 axis participates in retinal degeneration." (PMID 22536384, 2012). "Furthermore, mice deficient in CX3CR1 age-dependently develop AMD-like lesions, and mice deficient in both CCL2 and CX3CR1 have an early onset of retinal degeneration, although recent studies suggest that pathologies in the CCL2/CX3CR1 double knockout (DKO) mice is related to the Crb1 rd8 mutation." (PMID 23637822, 2013). "Using the CCL2/CX3CR1 double knockout mouse model (DKO), which demonstrates RPE damage and retinal degeneration, we uncovered an interaction between PEDF and the TEP which is likely to play an important role in retinal ageing and in the pathogenesis of AMD." (PMID 30160348, 2018). "Overall, this study reveals that the protective effects of microglia depletion in CX3CR1-WT mice are CX3CR1-dependent as microglia depletion in CX3CR1-KO and hCX3CR1I249/M280 mice did not alleviate retinal degeneration." (PMID 37033925, 2023). "In summary, the protective effects of microglia depletion is CX3CR1-dependent as microglia depletion in CX3CR1-KO and hCX3CR1I249/M280 mice did not alleviate retinal degeneration nor microglial morphological activation as observed in CX3CR1-WT mice." (PMID 37033925, 2023). "Compared to other models in which subretinal inflammation occurs secondarily to light-injury or genetic defects, the Cx3cr1 knockout mouse model presents a primary MP accumulation in the absence of an inherited retinal degeneration (C57BL/6J background)." (PMID 24142887, 2013). "More recently, we have shown that in the absence of CX3CR1, ischemia and oxidative damage-mediated retinal degeneration is accelerated." (PMID 23637822, 2013). "The lack of CX3CR1 may be responsible for the increased microglial activation and retinal degeneration in the DKO mice under ageing and light exposure conditions." (PMID 23637822, 2013).
retinal degeneration (continued). "Inversely, this shows that neither the single nor the double knockout of the chemokines Ccl2 and/or Cx3cr1 does lead to an early onset inferior retinal degeneration since all unaffected lines show a similar very low number of any autofluorescent lesions in the fundus as wildtype mice." (PMID 22545116, 2012). "The group also reported no retinal degeneration in 12–14 months old CCL2 KO, CX3CR1 KO and CCL2/CX3CR1 DKO mice housed under dim conditions (33 lux light intensity)." (PMID 23637822, 2013). "Ccl2 deficiency also does not significantly add to the exacerbated retinal degeneration seen in Cx3cr1−/−/Crb1RD8/RD8 mice suggesting that the effects of Ccl2 and Cx3cr1 signalling defects do not act synergistically on the manifestation of the retinal degeneration in Crb1RD8/RD8 mice." (PMID 22545116, 2012).
viral infection (28 papers, 2012 to 2025). "Expression of CX3CL1/CX3CR1 in viral infection and associated diseases." (PMID 38674036, 2024). "We further analyzed GP66+CD4+ T cells according to their expression of TCF1, a transcription factor intrinsically required for the differentiation of viral-specific Tfh cells, and CX3CR1, a maker of terminally differentiated Th1 cells in viral infections." (PMID 40956613, 2025). "Here, we identify YTHDC1 as a novel negative regulator of RSV viral infection by downregulating the expression of host cell RSV entry receptor CX3CR1." (PMID 38793659, 2024). "The work in models of viral infection has noted that either intermediate or high expression of CX3CR1 can be used to classify TM subsets with differential abilities to self-renew and traffic into peripheral tissues." (PMID 37414528, 2023). "CX3CL1 expression can be increased by inflammatory cytokines present during viral infections and, in cardiovascular disease, this chemokine increase in the vasculature leads to recruitment of CX3CR1+ T cells." (PMID 33653907, 2021). "CX3CR1+ CD8 T cells were recently identified as an effector subset with potent cytolytic function against chronic viral infection and cancer." (PMID 34302042, 2021). "In regions with more prolonged viral infection (i.e., the rostral region of the brain), infiltrating Ly6Chi macrophages had lower Ly6C expression and higher expression of CX3CR1, TMEM119, P2RY12, CD64, CD68 and MHC-II, compared to those in the caudal regions." (PMID 34311763, 2021). "CX3CR1 has recently been identified as a marker of CD8+ T cell memory during viral infection in murine models but the role if any of fractalkine in the differentiation of such T cells has not been described." (PMID 30150990, 2018). "To characterize CX3CR1 expression on CD8+ Tmem cells in persistent viral infection, we first analyzed the well-characterized model of MCMV infection." (PMID 29669283, 2018). "The main population of CD45-positive cells recruited in response to virus infection were monocytes (CD45high, Cx3Cr1+, CD11b+, Ly6Chigh, Ly6G− cells), which population was markedly reduced in the absence of functional microglia." (PMID 30027450, 2018). "Together, these results indicate that virus-specific CX3CR1+ memory T cells are also present during chronic viral infections albeit at much lower numbers than in resolved infection and that their numbers increase during successful therapeutic intervention." (PMID 26404698, 2015). "Moreover, the G protein contains the CX3C motif that binds the chemokine receptor CX3CR1 in respiratory epithelial cells, which plays an essential role in viral infection." (PMID 39066445, 2024). "Interestingly, Gcc shows no glycosylation and is highly conserved in subgroups A and B, which contain the CX3C motif that binds to the chemokine receptor CX3CR1 in human respiratory epithelial cells and plays an important role in viral infection and virus pathogenesis." (PMID 39066445, 2024). "Interestingly, CX3CR1 conditional knockout mice had significantly reduced levels of influenza m protein on day 7 of a single viral infection as compared to Cre- controls while still losing similar percentages of body weight and producing similar levels of type I IFNs in the lungs." (PMID 39178311, 2024). "To date, few studies have looked at the tissue localization of CX3CR1+ CD8+ T cell populations with recent reports of their migration to lymph nodes, spleen, bone marrow, lung, and liver in murine models of viral infection." (PMID 30150990, 2018). "Antigen-specific GFP+ (CX3CR1+) and GFPneg (CX3CR1neg) CD8+ T cells were found in the lymphoid tissue like in the spleen but also in the blood and liver after viral infection." (PMID 26404698, 2015). "We find low numbers of CX3CR1+ memory CD8+ T cells with effector function in patients suffering from chronic viral infection and high numbers in patients who recovered from viral infection." (PMID 26404698, 2015).
viral infection (continued). "Through this motif, the RSV G protein binds to the fractalkine receptor, CX3CR1, and facilitates virus infection." (PMID 23300550, 2012). "This complexity in macrophage populations, in the context of viral infections, is highlighted by the observation that CD14+CD16+ cells also expressed CD206 and LYVE, which characterized TRM cells, as well as expressing CD183 and CX3CR1." (PMID 37485876, 2023). "The previous study has indicated that CX3CR1 is not required for antigen recognition or effector differentiation following acute viral infection." (PMID 29669283, 2018). "This latter finding conflicts with previous data showing high cell surface expression of CX3CR1 on non-classical monocytes and their capacity to respond to damaged cells and viral infections." (PMID 26650546, 2015). "Of note, progeny CD8+ T cells were comprised of both, GFP+ (CX3CR1+) and GFPneg (CX3CR1neg) T cells, indicating that CX3CR1-expressing CD8+ T cells can arise from GFPneg (CX3CR1neg) memory CD8+ T cells during recall responses after viral infection." (PMID 26404698, 2015). "Interestingly, DoRothEA analysis predicted that the TF Zeb2, known to promote the function of long-lived effector cells (LLECs) and effector memory CD8 T cells in acute viral infection, is active in splenic effector memory, AY036118+, and Cx3cr1+ effector cells." (PMID 35667687, 2022). "For lymphocytes, CX3CR1 is expressed by cytotoxic, effector-like CD8+ T cells and NK cells and, in particular, expressed by a CD8+ T cell population that can interact with the vasculature with a proposed role in control of persisting and/or reactivating viral infection." (PMID 33653907, 2021). "Collectively, our results indicate that CX3CR1+CD11c+ DCs play an important role in generating rapid and effective NK cell activation and Ag-specific CD4+ T-cell responses after viral inoculation at peripheral sites, thereby inducing resistance to viral diseases." (PMID 31316515, 2019). "Since CX3CR1 is involved in inflammatory disorders, cardiovascular diseases and viral infection, and due to the lack of data regarding the role of CX3CR1 in viral experimental myocarditis, we aimed to investigate the pathophysiological role of CX3CR1 in experimental CVB3-induced acute myocarditis." (PMID 28800592, 2017).